CD34 (CD34 molecule)
Diseases named in the same sentence as CD34 in open-access papers (continued):
Sharing a sentence is not in itself a finding about the gene and the disease.
leukemia (continued). "In CD34+/CD38- leukemia stem cells, we found that MK256 induced differentiation and maturation." (PMID 36342456, 2022). "This leukemia was characterized by expansion of CD34+CD10+CD19+ population." (PMID 35115489, 2022). "In pediatric leukemia patients undergoing haploidentical HCT NK cell reconstitution was faster in CD3-/CD19- as compared to CD34+ selection (350 vs. 180 cells/μl, respectively, on Day +60), which reflects depletion of NK cells from the graft in the latter but not in the former." (PMID 36313879, 2022). "To determine whether the change in USP15 transcripts results in an increase in USP15 protein, we performed immunoblotting for USP15 in CD34+ cells and a panel of leukemia cell lines." (PMID 34465865, 2022). "Currently, CD34 is the only routinely used clinical marker to enumerate leukemia blasts." (PMID 36245043, 2022). "Cell surface proteins are used as CSC markers for different types of tumors, for example, cluster of differentiation 34-positive (CD34+)/CD38 − for leukemia cells, CD13/CD45/CD90 for liver cancer, CD117/CD90/epithelial cell adhesion molecule for lung cancer, and CD44 for colon and gastric cancers." (PMID 35148781, 2022). "Factors secreted from irradiated mesenchymal stromal cells (MSC) may exert genotoxic effects in human CD34+ cells, thereby potentially contributing to the pathogenesis of hematologic disorders such as leukemias." (PMID 35740549, 2022). "However, more recent evidence suggests that only the leukemia-initiating cells are located in the CD34+/CD38− compartment, while the (more proliferative) bulk of the blast cells is located in the CD34+/CD38+ compartment." (PMID 36142442, 2022). "In addition, the expression of IL-10R on leukemia stem cells (CD34+ CD38−) was lower than that on bulk blast cells." (PMID 34392305, 2021). "LSCs have a self-renewal capacity to generate large numbers of leukemia progenitor cells (CD34+CD38+) through the activation of several signaling pathways including WNT/β-catenin, Hedgehog (Hh), Notch, transforming growth factor-β (TGF-β)/Forkhead box O (FOXO), and Musashi 2 (Msi2)-Numb signaling." (PMID 34922630, 2021). "Additionally, there was not a significant change in the percentage of early hematopoietic cells (CD34+Linlow or CD34+Linlowc-Kit+) in the bone marrows of leukemia-bearing mice with both Ro 08-2750 doses." (PMID 33504942, 2021). "However, later findings indicate that Fc-mediated clearance of anti-CD38 conjugated cells was responsible for the low leukemia initiating cell (LIC) activity that had been observed in the CD34+/CD38+ fraction." (PMID 34736527, 2021). "The CD34 marker represents leukaemia stem cells, typically observed in AML29; the CD117 marker is the c-kit proto-oncogene encoding the receptor tyrosine kinase involved in the proliferation of leukaemia cells found in the stage one of myeloid differentiation." (PMID 33907248, 2021). "At the same time, AML cell lines were used as target cells to confirm the cytotoxic ability of IL-10 CAR-T which could effectively eliminate leukemia cells under the same condition as that of CD34+ UCB cells." (PMID 34392305, 2021). "Notably, MLL leukemia CD34+ cells showed reduced colonies in the LAMP5-AS1 knockdown groups than in the control group, demonstrating impaired proliferation and self-renewal potential of MLL leukemia CD34+ cells when LAMP5-AS1 was depleted." (PMID 32552847, 2020). "Moreover, we measured the proportion of CD34+ cells in primary samples, generally representing leukemia stem cells (LSCs) or normal hematopoietic stem/progenitor cells (HSPCs)." (PMID 32296014, 2020). "These CD34+ cells responsible for leukemia initiation and maintenance were termed LSC." (PMID 33322769, 2020). "RUNX1‐ETO expressing CD34+ cord blood cells maintain self‐renewal and multipotent differentiation, but when transplanted do not cause leukaemia in NOD/SCID mice, consistent with the transgenic mouse models." (PMID 34766123, 2020).
leukemia (continued). "Leukemia cutis may also show a pcALCL-like histology but usually expresses TdT, CD34, and/or CD117, and myeloid lineage markers such as myeloperoxidase." (PMID 32013101, 2020). "We demonstrated here for the first time that two ULK1 inhibitors, MRT 68921 and SBI-0206965, induced caspase-dependent apoptosis preferentially in FLT3-ITD-mutated leukemia cell lines and primary leukemic blasts obtained from FLT3-ITD AML patients, while sparing normal CD34 (+) cells." (PMID 32393312, 2020). "Strikingly, 2 days of BL-8040 monotherapy induced apoptosis and 40.2-fold mobilization of immature AML progenitors (CD45+/low CD34+ CD117+ HLA-DR+), resulting in a median decrease of 57.7% in the number of bone marrow leukemia progenitor cells out of total CD45+ CD34+ normal progenitor cells." (PMID 32754595, 2020). "Among these, CD34−/CD38+ as well as CD34−/CD38− subpopulations induced leukemia." (PMID 33322769, 2020). "The cells of CD34+ primary leukemia and CD38- KG-1, and TF-1 were separated by flow cytometry." (PMID 31307525, 2019). "A recent study identified the presence of CD34− leukemia-initiating cells (LIC) in primary KMT2A-rearranged ALL samples, which may partly explain the clinical findings of the present study." (PMID 31807115, 2019). "It is well-known that HAdV-B fiber pseudotyped HAdV-5 vectors could transduce hematopoietic cell lines, CD34+ blood cells and primary leukemia cells." (PMID 31014302, 2019). "Because ABCB1 was highly associated with CD34 and CD33 we postulated that ABCB1 may be a bystander effect inherent to a respective leukemia stem cell (LSC) phenotype." (PMID 31500210, 2019). "To determine whether such signatures were diagnostic for leukemia type, we analyzed bulk-RNA-Seq in a large un-annotated adult AML cohort consisting of 438 patients (Leucegene) and 16 donor CD34+CD45RA- cord-blood samples for the same gene modules." (PMID 31529053, 2019). "Since one cell with markers for stem cells such as CD34 for leukemia or CD133 for solid cancers could initiate cancer growth, the concept of cancer stem cells (CSC) was born." (PMID 31083587, 2019). "Although it would be interesting to develop a similar humanized mouse model in which healthy human hematopoietic cells and primary leukemic blasts presence in the same individual mouse, the availability of healthy human CD34+ progenitor cells from the very same leukemia patient is a limiting factor." (PMID 30871629, 2019). "It was also reported that overexpression of PD-1 on stroma/non-blast compartment and its ligands (PD-L1 and PD-L2) on CD34+ leukemia cells is associated with more aggressive leukemia and progression from Myelodysplastic syndromes (MDS) to AML or AML relapse." (PMID 31291985, 2019). "It has been shown that human leukaemia-initiating cells are often found within the CD34+ fraction." (PMID 30867444, 2019). "This has been convincingly shown for ROSlow quiescent CD34+ leukemia CSCs, lung spheroids and CD133+ PDAC cells, as well as CSCs-enriched spheroids form ovarian, cervical and papillary thyroid carcinoma that displayed a reprogrammed metabolism through TCA cycle." (PMID 30967773, 2019). "In addition, human NKG2A+ natural killer cells reconstituted in immunodeficient mice from human CD34+ cells were able to kill engrafted human primary leukemia or Epstein-Barr virus cell lines by lysis after intraperitoneal administration of antihuman NKG2A." (PMID 29850617, 2018). "There are several kinds of leukemia cells, including CD34+CD38− cells and CD34−CD38+ cells." (PMID 30310855, 2018). "However, xenotransplantation of CD34+CD38+CD19+ or CD34−CD19+ cells did lead to leukaemia development, and those cells expressed MLL-AF4." (PMID 28819864, 2018). "Similarly, the cancer‐germline gene PRAME is overexpressed in various cancer and leukemia types as well as in CML CD34+ cells." (PMID 29575763, 2018). "Similar to other pre-B ALL, the leukaemia blast population in patients is CD10+CD19+CD34+." (PMID 28819864, 2018).
leukemia (continued). "Furthermore, we found that the Nanog mRNA expression-level is higher in LSCs from leukemia cell lines and CD34+ cells from AML clinical samples." (PMID 30013477, 2018). "In one study, characterization of 5 AML samples via Affymetrix Hu133A microarrays allowed the identification of 261 DNA repair, signal transduction and cell cycle genes, the expression of which was significantly lower in AML-derived LSCs compared with CD34+CD38+ leukemia cells." (PMID 29466292, 2018). "To determine whether AF1q is a potential survival-related gene for CML leukemia stem cells, we measured its expression in CD34+ progenitor cells from newly diagnosed CP CML patients." (PMID 30154435, 2018). "The percentage of the CD34+ CD38low/− population at diagnosis strongly correlates with clinical outcome, in addition, survival and outgrowth of leukemia cells after therapy may depend on many factors including LSC load." (PMID 30344921, 2018). "To determine whether our ZFNs have effect on bcr-abl in primary leukemia stem/progenitor cells, we collected CD34+ cells from CML patients and transfected them with ZFN-L/R and donor." (PMID 29554925, 2018). "Therefore, we evaluated the capacity of light-inducible RA+NPs to prompt the differentiation of human CD34+ primary leukaemia cells isolated from the bone marrow aspirates of acute myeloid leukaemia (AML) patients, taken at diagnosis." (PMID 28492285, 2017). "Moreover, the CD34+ leukemia cells in the three APL patients were all located in the CD45dimSSClow area (purple cell population), and the remaining abnormal cells demonstrated intermediate SSC signals." (PMID 29113330, 2017). "As leukemia-initiating cells (LICs) – most frequently found within the CD34+/CD38− cell compartment – are supposed to be the source of relapse, we next analyzed the expression level of CD157 on CD45DIM, CD34+/CD38− cells of AML patients in comparison to leukemic bulk cells (CD45DIM)." (PMID 28415689, 2017). "The leukemia-cell- changes in BM-MSC were different that those induced by CD34+ cells." (PMID 28796790, 2017). "Analogous results were obtained in another leukemia stem-like cell line, CD34+CD38− Kasumi cells." (PMID 28814980, 2017). "In acute—myeloid leukemia (AML) CD34+ CD38− cells are a leukemia—initiating subpopulation." (PMID 29084232, 2017). "Crucially, the more differentiated CD34+CD38+ cells were unable to generate leukemia." (PMID 29034206, 2017). "Studies from clinical data and experimental systems have shown that AML originates from a rare population of LSCs (CD34+CD38- cells) or leukemia-initiating cells (LICs) which are capable of self-renewal, proliferation, and differentiation into malignant blasts." (PMID 27917123, 2016). "Besides CD7+/CD34+/− cell fractions from studied T-ALL samples with delayed leukemia development activity are either genetically heterogeneous or homogenous." (PMID 27191650, 2016). "In such slow developing T-ALL differential CD34 expression may thus distinguish genetically diverse cell fractions with distinct abilities to re-establish leukemia in mice or genetically homogenous cell fractions with a weak growing fitness in mouse." (PMID 27191650, 2016). "Kinetic analysis of CD7+/CD34+/− leukemic cell growth in vivo using immunohistochemistry did not allow early cell infiltration analysis but revealed higher late infiltration level for CD7+/CD34+-derived xenografts compared to CD7+/CD34−-derived leukemia in accordance with flow cytometry datas." (PMID 27191650, 2016). "Moreover, tetrandrine citrate has the capacity to inhibit the growth of IM-resistant CML K562, primary leukemia, and primitive CD34 (+) leukemia cells." (PMID 27027348, 2016). "While it is generally accepted that CD34 expression is diagnostic for precursor leukemia, there are no consensus criteria for differentiating true precursor leukemias from other forms of lymphoproliferative disease when CD34 expression is lacking." (PMID 28435836, 2016).
leukemia (continued). "Finally, we demonstrated that CD45 was differently organized on the cell surface, since CD45 colocalized more within lipid rafts on leukemia blasts than was the case in CD34+ cells." (PMID 27579617, 2016). "One example might be the culture of pro-survival proteins, like Bcl-2 and Bcl-XL with CD34+ leukaemia CSCs, thus diminishing apoptosis after chemotherapy." (PMID 27766946, 2016). "As for T-ALL1-3, CD34+ cells produced leukemia in xenograft faster meaning they were more aggressive than CD34− cells although increasing the injected cell number allowed to observe and quantify leukemia development also in CD7+/CD34− cells of all 3 slow-growing T-ALL." (PMID 27191650, 2016). "Similarly, previous studies have reported that in B-ALL, only CD34+CD38− cells can initiate leukemia in immunodeficient recipients." (PMID 28018598, 2016). "Interestingly, Ouabain was shown to be more effective at targeting the CD34+CD38− leukemic stem cell-like population than the CD34+CD38+ leukemia cells, which makes this type of compounds an interesting potential anti-LSCs drug candidate." (PMID 27110755, 2016). "Interestingly only xenografts from CD7+/CD34+ sorted T-ALL4 leukemic cells were able to initiate leukemia in secondary transplants in accordance with our previous results and secondary T-ALL were 100% IKZF1del positive cells." (PMID 27191650, 2016). "AE pre-leukemia stem cells are enriched in the CD34+ fraction." (PMID 27509060, 2016). "Recent study has shown that Ouabain targeted the CD34+CD38− population in human leukemia samples." (PMID 27110755, 2016). "In the case of delayed T-ALL growth CD7+/CD34+ or CD7+/CD34− cells were either genetically diverse, the resulting xenograft leukemia arising from different but branched subclones present in the original sample, or similar, indicating decreased fitness to mouse micro-environment." (PMID 27191650, 2016). "Multiple subclones were found in 2/3 samples unequally distributed within the CD7+/CD34+ and CD7+/CD34− fractions, and their respective frequencies as well as oncogenic events seem to play roles in the specific abilities of CD34+/− cells to perpetrate leukemia in xenograft models." (PMID 27191650, 2016). "Furthermore, TWIST-1 is aberrantly highly expressed in CD34+CD38− leukemia stem cell candidates and its expression declines with differentiation." (PMID 26023795, 2015). "CD200 was more frequent in secondary compared to de novo leukemia (p = 0.0006), in CD34 positive cases (p = 0.00001), in Bcl2 overexpressing cases (p = 0.01), in those wild-type Flt3 (p = 0.004) and with favorable or unfavorable compared to intermediate karyotype (p = 0.0003)." (PMID 26338961, 2015). "Therefore, we first isolated LSCs using magnetic sorting with the gold standard surface markers CD34 + CD38- from six leukemia cell lines." (PMID 25890196, 2015). "The presence of anomalous expression of CD7 in CD34+ cells was more frequent in high-risk MDS and might reflect progression to leukemia." (PMID 25924846, 2015). "Three-year OS was significantly reduced in patients aged ≥ 55 years compared to younger patients (21% vs 60%, p < 0.0001), in case of secondary AML (20% vs 43% in de novo leukemia, p = 0.0004), and in CD34 positive cases (23%, vs 53% in CD34- patients, p < 0.0001)." (PMID 26338961, 2015). "The existence of cancer stem cells was demonstrated in human leukemia, where limiting dilution xenotransplantation of CD34+/CD38− leukemic cells recapitulated the entire original tumor, whereas CD34+/CD38+ and CD34− leukemic cells were not tumorigenic at any cellular concentration." (PMID 25080108, 2014). "There is increasing evidence that FLT3-ITD has activity in hematopoietic stem cells, as demonstrated by the presence of ITD in the CD34+CD38− leukemia-initiating cell (LIC) population, and confirmation of the ITD mutation in these successfully engrafted LICs in a murine transplant model." (PMID 25295230, 2014).
leukemia (continued). "However, cancer initiating cells in other neoplasms have been characterized by at least 2 different surface markers; CD44+/CD24-/lin- in breast cancer, a2b5+/CD133- in glioblastoma and CD34+/CD38− in leukemia:." (PMID 25105565, 2014). "In order to assess whether these were clinically important, when present together with the leukemia initiating CD34+CD38- compartment, we assessed their prognostic impact." (PMID 25244440, 2014). "Moreover, STAT5 phosphorylation decreased considerably and PARP activity increased following co-treatment with imatinib and TG101348 in Ph+ leukemia cells including primary CD34-positive cells." (PMID 24775308, 2014). "STAT5pY694 was higher in all leukemia groups as compared to the CD34+ groups." (PMID 25568664, 2014). "Total STAT5 was significantly lower in all leukemia groups with respect to the CD34+ group." (PMID 25568664, 2014). "Similarly to what was done with the leukemia cell lines, to study the effects of BMSCs on CD34+ cells, gene expression profiles from CD34+ cell mono-cultures and co-cultures with BMSCs were analyzed by microarrays." (PMID 24304929, 2013). "The leukemia cell-induced changes in BMSCs were different than those induced by CD34+ cells." (PMID 24304929, 2013). "We then examined whether increased miR-150 expression could also promote differentiation of more heterogeneous CD34+ primary patient leukemia samples." (PMID 24086639, 2013). "The leukemia initiating cells was found within the CD34+CD38− cell compartment." (PMID 23667721, 2013). "Proteins overexpressed in CD34+ or LSC relative to their normal counterparts might be leukemia specific therapeutic targets." (PMID 24223100, 2013). "Finally, CD34+/CD38− cells have been identified as leukemia initiating cells in human acute myeloid leukemia." (PMID 23977261, 2013). "This study reveals for the first time that PRMT1, the predominant enzyme responsible for cellular protein arginine methylation, plays a crucial role in promoting erythroid differentiation in bipotent leukemia cells as well as in human primary CD34+ hematopoietic progenitor cells." (PMID 23483889, 2013). "One hundred blasts sorted for low expression of CD34 transferred the leukaemia onto tertiary mice and unsorted blasts from these tertiary mice have now been passaged through two more generations of mice, clearly demonstrating long-term self-renewal of these ‘mature’ B-ALL blasts." (PMID 23229821, 2013). "The CD34+CD38- cell subset was originally thought to contain all the leukaemia initiating cells." (PMID 23013471, 2012). "Hence, our data confirm that a DNA damage response can be induced in dormant CD34+CD38- leukaemia cells." (PMID 23013471, 2012). "HR after cleavage by a zinc-finger nuclease (ZFN) at the CCR5 locus in presence of cognate donor linear and circular episomes was more efficient in a panel of immortalized cell lines from human leukemia than in human stem cells, such as cord blood CD34+ hematopoietic cells and human ES cells." (PMID 22761925, 2012). "Based on the differential expression of miR-27a in leukemias versus CD34+ HSPCs, we hypothesized that miR-27a might have tumor suppressor functionality." (PMID 23236401, 2012). "Indeed, alternative splicing in all of the leukemia samples was more than twice the median level observed in the normal CD34+ cell samples." (PMID 21853052, 2011). "Furthermore, Icaritin was able to suppress the growth of primary CD34+ leukemia cells (CML) and Imatinib-resistant cells, and to induce apoptosis." (PMID 21887305, 2011). "Fretz and coworkers observed that at lower temperatures (4 to 12°C), L- and D-octa-arginine peptides partitioned across nuclear and cytoplasmic compartments equally, moving to the endosomes of CD34+ leukemia cells when ambient temperature rose to 30°C and higher." (PMID 21029412, 2010).